TAGLN2 (transgelin 2)
Diseases named in the same sentence as TAGLN2 in open-access papers (continued):
Sharing a sentence is not in itself a finding about the gene and the disease.
glioma (continued). "Similar to our patient-derived glioma tissues, cell lines expressing mutant IDH1 had decreased TAGLN2 protein levels compared to U87 MG IDH1/2 WT glioma cells." (PMID 30647847, 2018). "TAGLN2 mRNA levels were significantly different between IDH1/2 WT grade II (n=21), grade III (n=52) and grade IV (n=133) gliomas from the TCGA database (p< 0.0001)." (PMID 30647847, 2018). "Here, we have shown that TAGLN2 functions as an oncogene in IDH1/2 WT gliomas and is expressed at significantly higher levels in IDH1/2 WT gliomas due to TAGLN2 promoter hypermethylation and subsequent gene silencing in IDH1/2 mutant gliomas." (PMID 30647847, 2018). "Our in vitro studies were conducted using high grade glioma GBM30 neurospheres (primary) and U87 MG established cell lines since we found that GBMs (which are nearly all IDH1/2 WT) have significantly higher TAGLN2 levels than LGGs." (PMID 30647847, 2018). "Among the 175 significantly differentially expressed genes, we identified TAGLN2 as an upregulated gene in IDH1/2 WT grade II and III gliomas compared to IDH1/2 mutant tumors (p-value=7.73×10−5; FDR=0.053) in our institutional cohort." (PMID 30647847, 2018). "We are the first to identify TAGLN2 as a gene likely to be involved in the hypermethylator phenotype and further show that TAGLN2 undergoes epigenetic regulation in IDH1/2 mutant gliomas." (PMID 30647847, 2018). "Taken together, this study demonstrates a possible link between increased TAGLN2 expression, invasion and poor patient outcomes in IDH1/2 WT gliomas and identifies TAGLN2 as a potential novel therapeutic target for IDH1/2 WT gliomas." (PMID 30647847, 2018). "Findings of this current work prompted that Sal A maybe a promising drug and TAGLN2/PI3K/Akt pathway might serve as therapeutic targets, which are able to become prospective adjuvant in glioma chemotherapy clinically." (PMID 35505656, 2022). "To conclude, Sal A treatment could suppress the malignant behaviors of glioma cells and improve TMZ sensitivity through inactivating TAGLN2/PI3K/Akt pathway." (PMID 35505656, 2022). "Therefore, our data suggest that epigenetic silencing by promoter hypermethylation likely accounts for decreased TAGLN2 mRNA and protein levels observed in IDH1/2 mutant gliomas." (PMID 30647847, 2018). "Furthermore, our results suggest that TAGLN2 functions as an oncogene by contributing to proliferation and invasion when overexpressed in IDH1/2 WT glioma cells." (PMID 30647847, 2018). "We performed profiling of IDH1/2 WT versus IDH1/2 mutant Grade II and III gliomas and identified transgelin-2 (TAGLN2), an oncogene and actin-polymerizing protein, to be expressed at significantly higher levels in IDH1/2 WT gliomas compared to IDH1/2 mutant gliomas." (PMID 30647847, 2018). "The expression pattern and clinical significance of TAGLN2 in human gliomas, however, have not been determined." (PMID 29110682, 2017). "In addition, TAGLN2 and EMP3 were performed in commercially glioma tissue-microarrays." (PMID 33123464, 2020). "While in agreement with a recent study showing that TAGLN2 is a poor prognostic marker for gliomas, our study is the first to report that TAGLN2 is a negative prognostic factor associated with IDH1/2 WT gliomas and its regulation in gliomas is highly dependent on IDH1/2 mutation status." (PMID 30647847, 2018). "The function of Tagln2 has not yet been clarified, but recent reports have demonstrated that certain tumors, including those of colorectal cancer, bladder cancer, uterine cervical squamous cell carcinoma, esophageal squamous cell carcinoma and gliomas, exhibit Tagln2 overexpression." (PMID 34150622, 2021).
bladder cancer (19 papers, 2011 to 2025). "As a tumor suppressor, miR-145-5p directly targets and downregulates the expression of TAGLN2, a protein known to promote the motility and invasiveness of bladder cancer cells." (PMID 40689207, 2025). "Elevated expression of TAGLN2 has been reported in multiple malignancies, including colorectal cancer, bladder cancer, lung cancer, cervical squamous cell carcinoma, and breast cancer." (PMID 41169389, 2025). "In bladder cancer, miR-145-5p expression was significantly downregulated, whereas TAGLN2 expression was abnormally elevated." (PMID 40689207, 2025). "It is well documented that TAGLN2 functions as a pivotal driver in various types of cancers, including meningioma, bladder cancer, colorectal cancer, esophageal squamous cell carcinoma and so on." (PMID 35505656, 2022). "Further studies implied that transgelin-2 has a potentially oncogenic function in bladder cancer, both in vitro and in vivo." (PMID 31591355, 2019). "The expressions of microRNA-1 and microRNA-133a were previously reported to be down-regulated in bladder cancer tissues and showed functional significance in carcinogenesis via targeting TAGLN2 in the cancer cells." (PMID 25014919, 2014). "miR-1 has further been reported to be down-regulated and suggested a tumor-suppressive function by targeting the transgelin 2 gene (TAGLN2) in bladder cancer and head and neck squamous cell carcinomas." (PMID 22529906, 2012). "In addition, suppression of Tagln2 markedly decreased cell viability by inducing apoptosis in bladder cancer cell lines." (PMID 34150622, 2021). "Another study demonstrated that TAGLN2 could be a prospective tumor tissue marker for diagnosis and evaluating lymph node metastasis in bladder cancer patients." (PMID 33123464, 2020). "Our study presents the tumor suppressor characteristics of TAGLN in bladder cancer, both in vitro and in vivo, and agrees with the concept of that the role of transgelin-2 in tumor development might be contradictory to the role of TAGLN." (PMID 31591355, 2019). "Similarly, TAGLN2 has been reported as a target of miR-1 in renal cell carcinoma, bladder cancer and head and neck squamous cell carcinoma." (PMID 25196260, 2014). "In addition, miR-133a and the co-transcribed miR-1 were recently described to exhibit a reduced expression in prostate and bladder cancer in which miR-133a targets Transgelin 2 (TAGLN2), a gene with oncogenic properties that was strongly downregulated in our pSILAC dataset." (PMID 22532850, 2012). "Overexpression of miR-145-5p significantly inhibited the proliferation and migration ability of bladder cancer cells, as verified by MTT and Transwell assays, while high expression of TAGLN2 promoted these malignant phenotypes." (PMID 40689207, 2025). "Silencing of TAGLN2, a homologue of TAGLN, has been reported to significantly inhibit cell proliferation and increase apoptosis in bladder cancer." (PMID 34771544, 2021). "TAGLN2, which is homologous gene of TAGLN3, was reported to have tumour-suppressive function in bladder cancer." (PMID 27586240, 2016).
breast carcinoma (18 papers, 2011 to 2025). "A recent study exploring the role of TAGLN2 in cancer demonstrated its association with multidrug resistance and metastasis in breast cancer, emphasizing the potential of TAGLN2-targeted therapies." (PMID 38509504, 2024). "Taken together, we concluded that the loss of IFT20 promoted breast cancer cell migration partially by decreasing the expression of Tagln2." (PMID 33748116, 2021). "Moreover, while the differential expression of HSP90AA1 and TAGLN2 was closely linked to fibroblast differentiation, the precise molecular mechanisms underlying these changes, particularly in the context of different breast cancer subtypes, remain unclear." (PMID 40299459, 2025). "Our findings reveal new insights into the regulation of fibroblast differentiation and highlight TAGLN2 as a potential target for therapeutic strategies aimed at controlling fibroblast behavior in breast cancer." (PMID 40299459, 2025). "In paclitaxel-resistant breast cancer cells, salvianolic acid A downregulates the expression of TAGLN2 by activating the PI3K/Akt pathway, restoring chemoresistance to paclitaxel." (PMID 38509504, 2024). "Various studies have shown that potentially carcinogenic factor TAGLN2 is altered at the transcriptional and translational levels in a variety of malignancies, including as leukemia, breast cancer, colorectal cancer and lymphoma." (PMID 38818376, 2024). "Consistently, the downregulation of transgelin-2 promoted the metastasis of breast cancer cells by activating reactive oxygen species and the NF-κB signaling pathway." (PMID 33898417, 2021). "Along this line, there are reports that salvianolic acid A (SAA), a natural compound extracted from Salvia miltiorrhiza, reverses the paclitaxel resistance and migration and invasion abilities of MCF-7 breast cancer cells by inactivating transgelin-2." (PMID 33898417, 2021). "Meanwhile, TAGLN2 was suggested to be negatively correlated with breast cancer metastasis, and metastatic breast cancer cell line exhibited down-regulation of TAGLN2 protein." (PMID 29110682, 2017). "Among them apolipoprotein A-I and D, enolase 1, tumor rejection antigen (gp96) 1, transgelin 2, cofilin 1, profilin, heat shock proteins 70, and annexins 5 were found to be present in significant quantity in both types of breast cancer." (PMID 22110952, 2011). "Knocking down TAGLN2 may present as a target in breast cancer patients, based on reports that TAGLN2 knockdown increases DNA damage and sensitizes gastric cancer cells to chemotherapy and radiation." (PMID 41373732, 2025). "It has also been identified as a tumor suppressor in breast cancer metastasis, where its effects may be mediated by redox signaling, positioning TAGLN2 as a critical regulator of the ROS/NF-κB pathway in breast cancer." (PMID 40299459, 2025). "Downregulation of transgelin 2 is reported to promote breast cancer metastasis." (PMID 36873948, 2023). "It was demonstrated that paeonol reduces paclitaxel resistance in human breast cancer cells by regulating the expression of transgelin 2 and also exerts an anti-cancer effect on colon cancer cells by suppressing prostaglandin (PGE-2) synthesis and COX-2 expression." (PMID 36501418, 2022). "Because TAGLN2 KD in human breast cancer cells inhibited their migration and invasion, we performed the migration assay to examine whether TAGLN2 has a role of B cell migration." (PMID 28910360, 2017). "TAGLN2’s role in breast cancer metastasis was examined through transwell migration, luciferase, and flow cytometry assays, as well as a mouse xenograft model, suggesting TAGLN2 acts as a tumor suppressor, and its loss may enhance breast cancer metastasis via activation of the ROS/NF-κB pathway." (PMID 41373732, 2025). "Overexpression of TAGLN2 could suppress lung metastasis in a mouse model of breast cancer." (PMID 35869490, 2022).
breast carcinoma (continued). "Although no clinical trials are testing these compounds, inhibition of TAGLN2 may be pursued as a therapeutic option for breast cancer patients expressing high levels of this gene following confirmation of the prognostic impact of the protein in breast cancer patients." (PMID 41373732, 2025). "SB-T-121,205, a next-generation taxoid, shows antitumor activity by inhibiting the TAGLN2 and PI3K/Akt pathways in human breast cancer cells." (PMID 38509504, 2024). "Transgelin 2 directly interacts with PTEN to decrease PTEN expression and promotes paclitaxel resistance as well as the biological behaviours of breast cancer through regulating PI3K/AKT/GSK‐3β pathway." (PMID 34427967, 2021). "TAGLN2 overexpression activated the PI3K/Akt/GST-3β pathway and downregulated the expression of PTEN, which promoted paclitaxel treatment resistance and the migration and invasion of breast cancer cells." (PMID 39168971, 2024). "Transcript levels of five of the seven metabolic genes (TALDO1, GPI, SHMT2, LDHA, and ADK: 5-gene metabolic signature) and six oncogenes: TAGLN2, NOLC1, HSP90AB1, HDGF, MCM5, and NCL, were elevated in TNBC patients when compared to patients with ER+ breast cancer." (PMID 34711841, 2021). "Overexpression of transgelin-2 in cytotoxic CD8+ T cells increases adhesion to ICAM-1-positive E0771 breast cancer cells, but not ICAM-1-negative B16/F10 melanoma cells, suggesting the therapeutic potential of transgelin-2 in T-cell immunotherapy." (PMID 33898417, 2021).
colorectal cancer (15 papers, 2011 to 2025). A primary or metastatic malignant neoplasm that affects the colon or rectum. "In this study, we further demonstrated that the apoptosis induction and proliferation inhibition of human colorectal cancer cells SW620 were highly correlated with the expression of Transgelin-2 via activating the p38MAPK pathway to regulate cell cycle." (PMID 36204303, 2022). "In this study, we found Transgelin-2 regulated via p38 MAPK signaling in the colorectal cancer cells apoptosis by TanIIA." (PMID 36204303, 2022). "Transgelin-2 is abnormally and highly expressed in colorectal cancer, ovarian cancer, kidney cancer, gastric cancer, and other malignant tumors." (PMID 34234838, 2021). "Transgelin-2 is a cytoskeletal protein with actin-binding activity shown to be a tumor suppressor in colorectal carcinoma." (PMID 26955879, 2016). "Our results suggested that TanIIA could induce apoptosis of colorectal cancer and block the cells in G0/G1 phase involved in downregulating the expression of Transgelin-2 through p38MAPK signal pathway." (PMID 36204303, 2022). "Furthermore, some of the targets predicted by TaLasso for miR-1 were related to the cancers in MCC data: for instance, MCM7, related to prostate cancer progression and TAGLN2, a colorectal cancer biomarker." (PMID 22348024, 2012). "Furthermore, TAGLN2 has been identified as an oncogene related to prognosis and immunity across various cancers, and its involvement in tumor proliferation and migration in colorectal cancer has also been documented." (PMID 38509504, 2024). "In colorectal cancer (CRC) specifically, miR-133 has been reported to target multiple oncogenic factors including LASP1, TAGLN2, FSCN1, and COL1A1, thereby suppressing proliferation, migration, and invasion." (PMID 41300774, 2025). "It was demonstrated that increasing TAGLN2 expression was correlated with lymph node metastasis, distant metastasis, and the TNM classification in colorectal cancer." (PMID 21378409, 2011). "Since the previous studies of us found that colorectal cancer cells SW620 apoptosis upon the activation of p38 MAPK, we made a point that whether Transgelin-2 expression relevant to the p38 MAPK activity." (PMID 36204303, 2022).
gastric cancer (14 papers, 2005 to 2026). A primary or metastatic malignant neoplasm involving the stomach. "Our research demonstrated that aberrant upregulation of TAGLN2 is associated with gastric cancer progression, and inhibiting its expression renders gastric cancer cells more susceptible to chemotherapy and radiation." (PMID 39168971, 2024). "Of these, Tagln2 has previously been linked to angiogenesis, proliferation, migration, and epithelial–mesenchymal transition in GC, while Mbl2 gene variants have been linked to risk of stomach cancer and increased serum levels linked to pancreatic cancer." (PMID 38542101, 2024). "CFL1 showed higher disease specificity and pre-analytical stability than TAGLN2 across multiple non-gastric cancers and special-condition samples." (PMID 42192960, 2026). "Here, the function, molecular mechanism and potential clinical value of Tagln2 in gastric cancer (GC) angiogenesis were investigated." (PMID 34150622, 2021). "IHC images from three patients with weak, moderate and strong Tagln2 expression in ECs from gastric cancer were shown." (PMID 34150622, 2021). "Transgelin 2, which has been reported to be overexpressed in gastric cancer, was found to be upregulated in 11 of 16 HCC patients." (PMID 15756260, 2005). "In addition, some reports indicated that TAGLN2 was overexpressed in gastric cancers and hepatocellular carcinomas." (PMID 36333693, 2022). "Increased levels of transgelin-2 have been reported as associated with metastasis in several cancers, such as lung, bladder, colorectal, esophageal, and gastric cancer; moreover, its inhibition has negative effects on cancer cell migration and invasion." (PMID 35744062, 2022). "In gastric cancer (GC), we identify TAGLN2 as a key exosomal mediator." (PMID 41824788, 2026). "Our work suggests that TAGLN2, YBX1 and induced ISGs are novel predictive markers for clinical outcomes, and that targeting TAGLN2-mediated ISG upregulation is an attractive therapeutic sensitization strategy for gastric cancer patients." (PMID 39168971, 2024).
hepatocellular carcinoma (10 papers, 2011 to 2025). A malignant tumor that arises from hepatocytes. "Though over-expression of TAGLN2 was observed in hepatocellular carcinoma, lung adenocarcinoma, and pancreatic cancer, analysis of TAGLN2 in HNSCC has not yet been reported." (PMID 21378409, 2011). "This notion is reinforced by previous studies showing that TGF-β upregulates TAGLN2 expression in human adipocytes, promotes Smad4-dependent vascular invasion in hepatocellular carcinoma, and directly activates TAGLN2 transcription via the TGF-β/Smad4 pathway in colon cancer cells." (PMID 41169389, 2025). "Transgelin 2 was also proved to have relationship with hepatitis B and liver carcinoma." (PMID 24455688, 2013). "Proteins, such as the transgelin 2, may be a marker of carcinoma in the stomach and hepatomas." (PMID 24321467, 2013). "We analyzed previously published gene expression datasets and found marked TAGLN2 downregulation in dysfunctional and exhausted CD8+ T cells infiltrating human metastatic melanoma and murine hepatocellular carcinoma." (PMID 38168227, 2023). "Transgelin-2 is also known to be phosphorylated at S83 and S163 residues via PFTK1, a cdc2-related serine/threonine protein kinase that has been shown to confer cell migratory properties in hepatocellular carcinoma (HCC)." (PMID 33898417, 2021).
lung carcinoma (7 papers, 2015 to 2022). "For example, a high expression of TAGLN2 in tumor-derived lung cancer endothelial cells has been associated with clinical stage, tumor size, and tumor development in lung cancer tissues." (PMID 35281112, 2022). "High expression of Tagln2 in tumor-derived ECs from lung cancer was observed in our previous research and was associated with stage, tumor size, and histological neural invasion." (PMID 34150622, 2021). "For example, high expression of TAGLN2 in tumor-derived lung cancer endothelial cells was associated with clinical stage, tumor size, and tumor development in lung cancer tissues." (PMID 29110682, 2017). "Tagln2 is significantly induced in hypoxic lung cancer cells, accompanied by an increase in epithelial-mesenchymal transition (EMT) and resistance to γ-radiation via activation of the IGF1Rβ/PI3K/AKT pathway." (PMID 34150622, 2021). "Furthermore, TAGLN2 is overexpressed in lung cancer tissues, and its high expression is closely related to the clinical stages and lymph node metastasis of lung cancer." (PMID 34530821, 2021).